CRP (C-reactive protein)
Diseases named in the same sentence as CRP in open-access papers (continued):
Sharing a sentence is not in itself a finding about the gene and the disease.
Sepsis (continued). "A meta-analysis study evaluating the diagnostic performance of CRP in sepsis identified that CRP has a better-pooled sensitivity (80%) but only 61% specificity." (PMID 38247605, 2024). "This research concentrates on the significance of CAR in the pathological process of sepsis, its association with prognosis, and the latest developments in employing procalcitonin, lactic acid, CRP, and other potential biomarkers." (PMID 38938850, 2024). "Our findings revealed that proportions of DN B cells were positively correlated with APACHE II scores and CRP levels, and that a sustained increase in the proportion of DN B cells represents an independent risk factor associated with sepsis-related mortality." (PMID 39359725, 2024). "Confirming our findings, another study on the association between CRP levels and death in patients with sepsis showed that a CRP value >100 mg/dL on day 3 after hospital admission was linked to a fatal outcome." (PMID 39173664, 2024). "This systematic review aimed to analyse and compare the diagnostic accuracy of PSP, PCT and CRP regarding sepsis in the ICU." (PMID 39416748, 2024). "Further multivariate logistic regression analysis revealed that CRP and cf-DNA were independent risk factors for sepsis (p < 0.05), demonstrating moderate diagnostic value." (PMID 39457503, 2024). "Even after exclusion of patients with sepsis related to COVID-19 disease, the diagnostic value of CRP on day 1 to discriminate patients with septic shock (AUC = 0.436; 95% CI 0.371–0.500; p = 0.052) was poor." (PMID 37204560, 2024). "In conclusion, patients with UROP who have DM, higher SI, higher NLR, and increased levels of CRP are significantly associated with a higher likelihood of sepsis." (PMID 39064542, 2024). "Through their meta-analysis, Tan and colleagues found that CRP's diagnostic role for sepsis is significantly less accurate and less specific than PCT." (PMID 38684973, 2024). "Elevated CRP levels (>100 mg/L) were associated with a 50% increased risk of death (HR: 1.50, 95% CI: 1.12-2.01, p = 0.008) in sepsis, while in septic shock, the risk increased to 70% (HR: 1.70, 95% CI: 1.20-2.32, p = 0.002)." (PMID 39469363, 2024). "Cytokines and chemokines such as IL-6, IL-1ra, and IL-8 have been demonstrated to have diagnostic utility as early sepsis markers, while acute phase reactants such as CRP and PCT rise during the later phases of systemic inflammation." (PMID 38312920, 2024). "Another study showed that SAA had overall better diagnostic accuracy in predicting neonatal late-onset sepsis compared to CRP and specificity." (PMID 38182736, 2024). "This study indicates that the HbA1c level was a significant predictor associated with sepsis in diabetic patients with UTIs, after the exclusion of infection-related blood indicators (CRP and WBC)." (PMID 38771840, 2024). "Then, we performed multivariable MR analysis using covariates known to be associated with sepsis such as CRP, type 2 diabetes, and neutrophil counts." (PMID 38459230, 2024). "According to Lin, damage to the heart, liver, kidneys, and other organs, along with laboratory abnormalities such as D-dimer, CRP, and increased cytokines are similar to the sepsis condition caused by bacterial infections." (PMID 39504070, 2024). "Common inflammation indicators such as C-reactive protein and procalcitonin levels were higher, making patients with severe sepsis more susceptible to platelet decrease." (PMID 39033248, 2024). "Pre-operative laboratory parameters, including White Cell Count (WCC), Haemoglobin (HB), and C-Reactive Protein (CRP), were assessed and higher CRP values were observed in patients at higher risk for early mortality, potentially indicating ongoing sepsis." (PMID 39274440, 2024).
Sepsis (continued). "For this reason, we enrolled critically ill dogs with a serum CRP at admission in ER above 1.6 mg/dL, as previously suggested, with the purpose of evaluating the diagnostic value of new-onset OD for sepsis diagnosis, as well as its prognostic potential." (PMID 38638640, 2024). "In univariate analysis, age, Hb, MO#, NLR, NMR, PLT, NeuX, NeuY, MonX, MonY and CRP were found to be associated with sepsis." (PMID 38337856, 2024). "While prior studies have shown a significant association between higher CRP and sepsis, and one study reported an impressive AUROC of 1.0 in diagnosing upper UTIs, our results do not support these findings." (PMID 38542009, 2024). "While the diagnostic performance of serum CRP in 68 hospitalized hemodialysis patients indicating severe infections and sepsis with a CRP cutoff of 11.2 mg/L, yielded a sensitivity of 89%, the specificity was only 48%22." (PMID 37016028, 2023). "Significant variables for the prediction of disease progression underlying the sepsis-1/2 definition were CRP, body temperature, SAH, and potassium." (PMID 37628779, 2023). "It was shown that patients with sepsis and an average CRP concentration of 207.8 mg/L have a higher risk of septic shock." (PMID 37371588, 2023). "The results indicate a significant positive association between CRP levels and a higher risk of sepsis as well as sepsis under 75 years old." (PMID 37662942, 2023). "The study showed that in adult patients with sepsis, the nCD64 index is an excellent biomarker with a diagnostic accuracy outperforming both CRP and PCT determinations." (PMID 37189528, 2023). "The mediation analysis revealed that CRP plays a significant role (32.02% mediation effect) in the causal pathway from Phylum Tenericutes and class Mollicutes to sepsis (in individuals under 75 years old)." (PMID 37662942, 2023). "For example, miR-122 plays a crucial role in the septic process and has a higher diagnostic value than CRP and leukocyte count; it has also been shown to be a prognostic marker for sepsis, albeit with low specificity and sensitivity." (PMID 37686271, 2023). "CRP has diagnostic value to discriminate sepsis and prognostic value to predict mortality in patients initiating CRRT." (PMID 36832265, 2023). "In adult patients with ED with suspected infection, the diagnostic accuracy for sepsis of LBP was similar to that of CRP but lower than that of PCT." (PMID 36878489, 2023). "The incidence of severe sepsis and the concentrations of inflammatory factors (CRP, PCT, TNF-α) in sepsis caused by G (−) bacteria were higher than those caused by G (+) bacteria." (PMID 38037118, 2023). "Changes in serum CRP levels are not only a diagnostic tool for sepsis and infection but also an indicator of inflammation evolution." (PMID 37189057, 2023). "C-reactive protein (CRP), an acute fluid phase protein, is closely associated with inflammation and infection, particularly sepsis, and can activate macrophages." (PMID 38027963, 2023). "A number of studies have shown that CRP, IL-6, and other markers have more diagnostic value in sepsis." (PMID 36691469, 2023). "The diagnostic performance of the sCD137 analysis for the sepsis diagnosis is comparable to the diagnostic accuracy of CRP and procalcitonin." (PMID 38139346, 2023). "This study aimed to estimate calprotectin levels in newborns with clinical sepsis and compare its diagnostic accuracy with other sepsis markers such as blood culture, CRP, and serum procalcitonin." (PMID 37600908, 2023). "Thirdly, the number of loci related to CRP is relatively small compared to those associated with sepsis and gut microbiota." (PMID 37662942, 2023). "IL-6 positively correlated with CRP in our SIRS/sepsis cohort (r = 0.230, p = 0.006), and this association was still significant when the patients with liver cirrhosis were excluded (r = 0.298, p = 0.001)." (PMID 38139346, 2023). "As a traditional inflammatory marker, CRP has proven its potential as an independent sepsis risk factor." (PMID 37197571, 2023).
Sepsis (continued). "Early sepsis causes a significant increase in the concentration of CRP, and because of this, it has been employed to diagnose sepsis and its prognosis." (PMID 37627950, 2023). "The diagnostic indicators of sepsis mainly include body temperature, heart rate, respiratory rate, white blood cell count, serum C-reactive protein (CRP), and procalcitonin (PCT) and other biochemical indicators." (PMID 37292192, 2023). "In our study, the serum concentration of CRP proved to be the most important feature associated with sepsis, though its importance value was still only 0.37." (PMID 36834338, 2023). "The median serum and salivary CRP values were significantly different across the three groups (culture-positive sepsis, neonates with probable sepsis, and neonates only with risk factors)." (PMID 36900011, 2023). "Persistent elevation of CRP is observed in some sepsis survivors and is associated with increased risk for rehospitalization and/or death." (PMID 36936903, 2023). "To gain a deeper insight into the association between gut microbiota, C-reactive protein (CRP), and sepsis, we conducted several Mendelian randomization (MR) analyses." (PMID 37662942, 2023). "A previous study reported that the SOFA score and CRP can be combined to evaluate the risk of sepsis after LT." (PMID 38093977, 2023). "Sepsis induced by LPS injection also caused a significant increase in serum CRP levels compared with the control group." (PMID 36611198, 2023). "Many developments in the rapid immunoassay of CRP for the diagnosis of neonatal sepsis are underway, which can only emphasize the diagnostic precision that it allows when discussing sepsis." (PMID 39554800, 2023). "In our examination of the relationship between CRP and sepsis, we found that CRP is associated with a higher incidence of sepsis and sepsis-related deaths among those under 75 years of age." (PMID 37662942, 2023). "Research has shown that CRP is a significant indicator of sepsis risk and a predictor in neonates and adults." (PMID 37197571, 2023). "In the same study, the median salivary CRP levels were significantly different among neonates with culture-positive sepsis, screen-positive sepsis, and neonates with only risk factors for sepsis." (PMID 36900011, 2023). "As the research for sepsis advances, a number of prognostic predictors associated with sepsis, such as procalcitonin, C-reactive protein, and lactic acid, have been proposed." (PMID 37849826, 2023). "C-reactive protein has also been identified as one of important risk factors for positive blood cultures in sepsis patients." (PMID 37301921, 2023). "Several cross-sectional studies have demonstrated that elevated CRP levels are linked to increased morbidity and mortality in sepsis." (PMID 37662942, 2023). "Interleukin-6 had a superior diagnostic value compared with PCT and even CRP in patients with ED diagnosed with sepsis." (PMID 36878489, 2023). "The diminished risk of sepsis and a high qSOFA score with a better decline of CRP levels were found after the PEIDF procedure among patients with poor physical health." (PMID 35884964, 2022). "COVID-19 infection is associated with the increased production of pro-inflammatory cytokines, C-reactive protein, increased risk of pneumonia, sepsis, acute respiratory distress syndrome, and heart failure." (PMID 35371397, 2022). "Collectively, nCD64 plus CRP performed best in prediction, discrimination, and reclassification of the 28-day mortality risk in sepsis." (PMID 35907785, 2022). "C-reactive protein after 24 h and white blood cell counts after 48 h were independent predictors of both sepsis (p = 0.021 and p < 0.001) and sepsis-associated mortality (p = 0.024 and p = 0.006, respectively)." (PMID 35887719, 2022).
Sepsis (continued). "Other studies revealed that the progress of COVID-19 infection was associated with the increased production of C-reactive protein, pro-inflammatory cytokines, and increased risk of pneumonia, sepsis, acute respiratory distress syndrome and heart failure." (PMID 36501059, 2022). "Both PCT and CRP have moderate diagnostic value for sepsis, but it is still limited to diagnose sepsis as a single index." (PMID 35309171, 2022). "Of special interest is our finding that the sepsis cause of deaths increased in a dose dependent manner with the quartiles of the first and second CRP." (PMID 35683538, 2022). "Our observation that children with complement variants had increased odds of thrombocytopenia, hyperferritinemia, and having a CRP > 10 mg/dl suggests that these variants convey risk for microangiopathy during episodes of severe sepsis." (PMID 34973142, 2022). "Procalcitonin (PCT) and C-reactive protein (CRP) are the two most commonly used diagnostic biomarkers used in sepsis." (PMID 36158418, 2022). "Previous studies have shown that delirium and sepsis in patients after hip surgery are also associated with elevated CRP levels." (PMID 36051706, 2022). "We show that sustained elevation of sBTLA one week after hospital admission is associated with late mortality in patients with BSI and sepsis, and that sBTLA concentration is associated with CRP and decreased lymphocyte count." (PMID 35312715, 2022). "Although a meta-analysis illustrated that nCD64 showed a diagnostic performance for sepsis superior to CRP and PCT regarding the monitoring of antibiotics treatment, our findings suggest that nCD64 index had an equivalent value to CRP and PCT." (PMID 35967346, 2022). "Does sepsis-associated immunosuppression render a PCT/CRP biomarker-guided antibiotic duration intervention ineffective?" (PMID 36600326, 2022). "Patients with an extremely low level of CRP (first quartile) not only had a better survival rate, but also had a lower risk of mortality from sepsis compared to patients in the highest quartile of either the first or second measurement of CRP." (PMID 35897672, 2022). "Humoral biomarkers, including procalcitonin (PCT), C-reactive protein (CRP), lactate and other dysregulated blood noncoding RNAs, are generally employed in clinical practice to help physicians assess sepsis and perform risk stratification." (PMID 35663956, 2022). "As a result, the increase in CRP serum level found in the present study was attributed to the inflammatory process associated with sepsis." (PMID 35208760, 2022). "In a recent study, albumin and CRP were indicated as risk factors that independently affect 28-day mortality in sepsis patients over 65 years of age (p<.001)." (PMID 36465747, 2022). "C-reactive protein (CRP) has only limited diagnostic potential in the early stages of sepsis due to the delayed induction of its hepatic synthesis and the presence of other infection-independent inductive factors." (PMID 36699313, 2022). "nCD64 plus CRP performed best in prediction, discrimination, and reclassification of the 28-day mortality risk in sepsis." (PMID 35907785, 2022). "The diagnostic value of the changed miRNA in sepsis was determined and compared with CRP and WBC by analysing the receiver operating characteristic (ROC) curves." (PMID 35907902, 2022). "Further studies investigating the effects of CRP treatment on sepsis-associated AKI, focusing on CD56+ NK cells and CD56+ T cells are anticipated in the future." (PMID 35008905, 2022). "An elevated C‐reactive protein/albumin ratio (CRP/ALB) 72 h after admission indicates an increased risk of mortality in patients with sepsis." (PMID 35182022, 2022). "CRP is an acute-phase inflammatory serum protein that rapidly responds to infection, and has proved valuable for early risk stratification of sepsis-suspected mortality in patients." (PMID 34434979, 2021).
Sepsis (continued). "More investigations are needed to explore novel diagnostic tools of burn sepsis due to the unreliability and limitation of the established biomarkers (CRP, PCT and cytokines)." (PMID 33654698, 2021). "The aim of this study was to evaluate the association of interleukin-6(IL-6), procalcitonin (PCT) and CRP with subsequent sepsis severity and mortality in preterm infants suspected of late onset neonatal sepsis." (PMID 33407770, 2021). "Studies have shown the usefulness of sequential measurements of CRP as a tool in the follow-up of different conditions such as community-acquired Pneumonia, ventilator-associated pneumonia, bloodstream infection and sepsis." (PMID 34863104, 2021). "miR-122 is another important miRNA in the sepsis which has superior diagnostic power compared with CRP and total leucocytes count for distinguishing sepsis from wound infection." (PMID 34956235, 2021). "In this large retrospective study, we assessed the association between IL-6, PCT and CRP at onset and subsequent sepsis severity and mortality." (PMID 33407770, 2021). "In the present study, we found that high CRP was associated with sepsis; however, this association was dependent on injury severity/patient factors." (PMID 34065206, 2021). "Taken together, these data demonstrate that the sepsis caused by Gram-positive bacteria is a less stimulus for the production of CRP, the data for this group are more variable, and although, the median values do not differ." (PMID 34840718, 2021). "Biomarker levels of IL-6, PCT and CRP were associated with this composite outcome of sepsis severity, in which PCT had the highest diagnostic accuracy." (PMID 33407770, 2021). "In this study, inflammation-related markers PCT, CRP, NLR, MLR, PLR, and CRP*PCT can be used as independent risk factors affecting the prognosis of patients with sepsis." (PMID 34233608, 2021). "Several nanodiagnostic platforms to detect sepsis-associated biomarkers, including bacteria, CRP, PCT, and cytokines, are discussed in this section." (PMID 33717630, 2021). "In the present study, we assessed the association of CRP with EVs in plasma from sepsis patients and tested the capacity of PentraSorb to deplete CRP-carrying EVs from septic plasma in vitro." (PMID 33772103, 2021). "This is the first observational study exploring the long-term effects of a single episode of sepsis on the lipid profile components and CRP as markers of risk factors for acceleration of atherosclerotic disease." (PMID 34869619, 2021). "In this study, we tested the diagnostic performance of MDW in predicting sepsis and compared it with those of conventional biomarkers (CRP, PCT, and WBC count)." (PMID 33857210, 2021). "Here, we characterized the association of CRP with EVs in plasma from sepsis patients using flow cytometry, and found highly elevated levels of total EV counts and CRP+ EVs as compared to healthy individuals." (PMID 33772103, 2021). "While concentrations of 120 μg/mL CRP are measured in clinical settings in neonates, we focused on the cut-off concentration of CRP associated with infections to evaluate the diagnostic potential of CRP upon on-set of sepsis." (PMID 33673378, 2021). "The combination of MNeV with CRP showed a good diagnostic performance for either suspecting or ruling out late-onset sepsis in their series." (PMID 33777867, 2021). "Noteworthy, both CPD parameters showed good diagnostic accuracy for sepsis, superior to traditional biomarkers, such as CRP and PCT." (PMID 34679578, 2021). "Biomarkers such as C-reactive protein and procalcitonin have been repeatedly shown as robust diagnostic markers for sepsis and septic shock." (PMID 34065206, 2021). "In the present study, we confirmed that CRP at onset of sepsis yields limited information on subsequent sepsis severity and risk of mortality." (PMID 33407770, 2021). "In conclusion, our study demonstrates that platelet-derived circulating EVs are associated with CRP in sepsis." (PMID 33772103, 2021).